REXO1L2P (REXO1 like 2, pseudogene )
Gene: Long non-coding RNA gene on chromosome 8 (85,826,865 to 85,827,942, reverse strand). Ensembl gene ENSG00000293002.
Diseases named in the same sentence as REXO1L2P in open-access papers:
REXO1L2P is named in the same sentence as 1 disease in open-access papers, as found by Europe PMC text mining. Sharing a sentence is not in itself a finding about the gene and the disease.
REXO1L2P shares sentences with these, for which no sentence is quoted: Nephropathy (1 paper).